ZNF541 (zinc finger protein 541)
Description:
Transcription regulator which is essential for male fertility and for the completion of meiotic prophase in spermatocytes. Regulates progression of the pachytene stage of meiotic prophase by activating the expression of genes involved in meiosis during spermatogenesis. Maintains the repression of pre-pachytene transcriptional programs, including meiotic double-strand breaks (DSB) formation genes in pachytene spermatocytes and suppresses aberrant DSB formation after mid-pachytene, thus ensuring meiosis progression.
Synonyms: DKFZp434I1930
Tractability: PROTAC: ubiquitination databases record sites on it.
Gene: Protein-coding gene on chromosome 19 (47,520,690 to 47,573,148, reverse strand). Ensembl gene ENSG00000118156.
Subcellular location: Nucleus
Subcellular location (Human Protein Atlas): Nucleoplasm; Cytosol
Gene Ontology:
Molecular function: protein binding; transcription corepressor activity
Biological process: male meiotic nuclear division; negative regulation of DNA-templated transcription; positive regulation of DNA-templated transcription; regulation of DNA-templated transcription; regulation of transcription by RNA polymerase II
Cellular component: histone deacetylase complex; nucleus; transcription regulator complex
Genetic constraint (gnomAD): Loss-of-function variants: 23 observed, 117.25 expected, observed/expected ratio (o/e) 0.2, 90% interval 0.14 to 0.28. The upper end of that interval is the gene's LOEUF score, 0.28, which puts it in group 1 of 6, group 1 being the genes least tolerant of losing a copy. Missense variants: 1,612 observed, 1,757.8 expected, observed/expected ratio (o/e) 0.92, 90% interval 0.88 to 0.96. Synonymous variants: 751 observed, 735.49 expected, observed/expected ratio (o/e) 1.02, 90% interval 0.96 to 1.09.
Homologues: Orthologues: chimpanzee ZNF541 (99% identical), macaque ZNF541 (95% identical), dog ZNF541 (82% identical), rabbit ZNF541 (78% identical), pig ZNF541 (78% identical), mouse Zfp541 (76% identical), rat Zfp541 (73% identical), guinea pig ZNF541 (71% identical), zebrafish znf541 (16% identical), Caenorhabditis elegans saeg-1 (12% identical), Caenorhabditis elegans Y105C5A.1 (8% identical), Drosophila melanogaster CG16779 (7% identical), and 3 more. Paralogues in human: TRERF1 (20% identical), MIDEAS (18% identical), RCOR3 (7% identical), RCOR2 (7% identical), RCOR1 (5% identical).
Diseases named in the same sentence as ZNF541 in open-access papers:
ZNF541 is named in the same sentence as 7 diseases in open-access papers, as found by Europe PMC text mining. Sharing a sentence is not in itself a finding about the gene and the disease. The quoted sentences say what the papers report.
breast carcinoma (2 papers, 2021 to 2022). "Multivariate Cox regression analysis of the two databases showed that high expression of ZNF644 and low expression of ZNF341, ZNF541, and ZNF653 were associated with radiosensitivity of breast cancer." (PMID 34504527, 2021). "Low expression levels of ZNF541 were related to the radiosensitivity of breast cancer." (PMID 35846149, 2022). "High expression of ZNF644 and low expression levels of the other 3 genes (ZNF341, ZNF541, and ZNF653) were related to the radiosensitivity of breast cancer." (PMID 34504527, 2021).
cervical cancer (1 paper, 2021). A primary or metastatic malignant neoplasm involving the cervix. "ZNF541 encodes a zinc finger protein supposed to be a component of chromatin remodeling complexes and previously suggested to play a role in the differential expression of genes according to HPV status in cervical cancer tissues and cell lines." (PMID 34298834, 2021).
head and neck cancer (1 paper, 2024). A primary or metastatic malignant neoplasm affecting the head and neck. "There has been previous evidence of differential expression of e.g. NEFH, ZRF2,TAF7L, ZNF541 and TYMS in head and neck cancer, related to HPV status." (PMID 38643268, 2024).
oropharyngeal cancer (1 paper, 2022). Carcinoma, predominantly squamous cell, arising from the epithelial cells of the oropharynx. "However, ZNF541 expression level was independently associated with a better OS of HPV-positive oropharyngeal cancer, which is similar to our study." (PMID 35846149, 2022).
cancer (1 paper, 2022). A tumor composed of atypical neoplastic, often pleomorphic cells that invade other tissues. "Among them, 8 of 12 hub genes (EPHX3, SPINK7, FCRLA, MASP1, ZNF541, CD5, BEST2, ZAP70) seemed to be cancer-promoting genes as they were downregulated in the high-risk group." (PMID 35846149, 2022).
tumours (1 paper, 2024). "A small number of genes were found significantly differentially expressed in HPV-positive versus HPV-negative tumours (for example NEFH, ZFR2, TAF7L, ZNF541, and TYMS)." (PMID 38643268, 2024).
ZNF541 also shares sentences with these, for which no sentence is quoted: testicular germ cell tumor (1 paper).